HSPA13 (heat shock protein family A (Hsp70) member 13)
Description:
Has peptide-independent ATPase activity.
Synonyms: STCH
Tractability: Antibody: UniProt predicts a signal peptide or a membrane-spanning region; its Gene Ontology location is reachable by antibodies, with medium confidence. PROTAC: ubiquitination databases record sites on it; its protein half-life has been measured.
Gene: Protein-coding gene on chromosome 21 (14,371,115 to 14,383,484, reverse strand). Ensembl gene ENSG00000155304.
Subcellular location: Microsome; Endoplasmic reticulum
Pathways (Reactome):
Cellular responses to stimuli: Regulation of HSF1-mediated heat shock response
Gene Ontology:
Molecular function: protein binding; ATP hydrolysis activity; heat shock protein binding; protein folding chaperone; ATP binding
Biological process: protein refolding
Cellular component: extracellular exosome; cytosol; intracellular membrane-bounded organelle; nucleus; plasma membrane; endoplasmic reticulum
Genetic constraint (gnomAD): Loss-of-function variants: 28 observed, 38.24 expected, observed/expected ratio (o/e) 0.73, 90% interval 0.54 to 1. The upper end of that interval is the gene's LOEUF score, 1, which puts it in group 4 of 6, group 1 being the genes least tolerant of losing a copy. Missense variants: 450 observed, 587.31 expected, observed/expected ratio (o/e) 0.77, 90% interval 0.71 to 0.83. Synonymous variants: 192 observed, 215.11 expected, observed/expected ratio (o/e) 0.89, 90% interval 0.79 to 1.01.
Homologues: Orthologues: chimpanzee HSPA13 (99% identical), dog HSPA13 (96% identical), macaque HSPA13 (94% identical), pig HSPA13 (93% identical), rat Hspa13 (91% identical), mouse Hspa13 (91% identical), rabbit HSPA13 (89% identical), guinea pig HSPA13 (76% identical), tropical clawed frog hspa13 (73% identical), zebrafish hspa13 (64% identical), Caenorhabditis elegans stc-1 (42% identical). Paralogues in human: HSPA8 (38% identical), HSPA1L (38% identical), HSPA2 (37% identical), HSPA6 (37% identical), HSPA5 (37% identical), HSPA1A (37% identical), HSPA1B (37% identical), HSPA9 (35% identical), HSPA4 (27% identical), HSPA4L (26% identical), HSPH1 (25% identical), HSPA14 (25% identical), and 1 more.
Diseases named in the same sentence as HSPA13 in open-access papers:
HSPA13 is named in the same sentence as 31 diseases in open-access papers, as found by Europe PMC text mining. Sharing a sentence is not in itself a finding about the gene and the disease. The quoted sentences say what the papers report.
colon cancer (3 papers, 2021 to 2023). "Despite some studies claiming that HSPA13 is highly expressed in gastric and colon cancer and associated with the recurrence of oral cancer, there is still a lack of research on its role and mechanism in HCC." (PMID 38062023, 2023). "HSPA13 has been recognized as a proto-oncogene in various cancers, including colon cancer, breast cancer, and cutaneous melanoma." (PMID 38062023, 2023). "For example, in colon cancer, knockdown of HSPA13 accelerates apoptosis and necrosis, facilitating ubiquitination of RIP1 in response to TNFα induction." (PMID 38062023, 2023).
gastric cancer (3 papers, 2010 to 2021). A primary or metastatic malignant neoplasm involving the stomach. "HSPA13 was mainly expressed in lung cancer, stomach cancer and endometrium cancer cell lines." (PMID 34712697, 2021).
lupus (3 papers, 2020 to 2025). "In this study, we identified Hspa13 as a novel positive regulator of IL‐10 producing Bregs and demonstrated that Hspa13 deficiency in MZ B cells contributed to lupus disease pathology by reducing Tregs." (PMID 39737854, 2025). "Therefore, our findings support the idea that Hspa13 deficiency in MZ B cells impaired their immune regulatory function in attenuating lupus pathology of MRL/lpr mice." (PMID 39737854, 2025). "Importantly, we proved that the deficiency of Hspa13 contributed to impaired IL‐10 production and immune regulatory function of MZ B cells, both in vitro and in lupus mice." (PMID 39737854, 2025). "Hspa13 deficiency in B cells derived from the CD19creHspa13fl/fl mice impaired their regulatory functions and therapeutic roles in improving the symptoms of lupus mice." (PMID 39737854, 2025). "However, the molecular basis underlying the role of Hspa13 in regulating Bregs function and lupus pathogenesis remains unclear." (PMID 39737854, 2025). "Functional decline of Bregs is accompanied with decreased Hspa13 expression in Bregs and MZ B cells in lupus MRL/lpr mice." (PMID 39737854, 2025). "Treg frequency, autoantibodies, and renal pathological changes were detected to assess Hspa13 function in determining Breg function and improving lupus pathology." (PMID 39737854, 2025). "HSPA13 is reported to be increased in B220+ cells from patients with multiple myeloma or systemic lupus erythematosus, whereas mice with B cell–specific deletion of HSPA13 have a reduction in plasmablasts, plasma cells, and antibody induction." (PMID 34613781, 2021). "Our finding also inspires further investigations to uncover the mechanistic link between HSPA13 and autoimmune diseases such as multiple myeloma or systemic lupus erythematosus." (PMID 34613781, 2021). "Critically, the Hspa13 cKO reduced the number of autoantibodies and the level of proteinuria in the pristane-induced lupus and lupus-prone MRL/lpr mouse models." (PMID 32547538, 2020). "We found that Hspa13 cKO reduced the number of autoantibodies and level of proteinuria in the mouse model with pristane-induced lupus." (PMID 32547538, 2020). "Collectively, our data suggest that Hspa13 was increased in PC-associated diseases (e.g., MM and SLE), whereas the B-cell-specific KO of Hspa13 reduced the production of autoantibodies and proteinuria in the lupus mouse model." (PMID 32547538, 2020). "We found that Hspa13 cKO reduced the number of autoantibodies and the level of proteinuria in the lupus-prone MRL/lpr mouse model." (PMID 32547538, 2020). "We found that Hspa13 mRNA was increased in PCs from atacicept-treated lupus-prone mice and in LPS-stimulated plasmablasts (PBs) and PCs." (PMID 32547538, 2020). "Thus, our results reveal a novel role of Hspa13 in regulating MZ B cell function and affecting lupus pathogenesis." (PMID 39737854, 2025). "Importantly, the decline of Bregs function supporting Treg differentiation was accompanied by decreased Hspa13 expression in lupus MRL/lpr mice." (PMID 39737854, 2025). "Thus, our results illustrate a vital role of Hspa13 in promoting IL‐10 producing Bregs production and regulatory function, and partially elucidates the reason for the impaired regulatory function of the MZ B cells in lupus‐prone mice." (PMID 39737854, 2025). "In lupus MRL/lpr mice, a decline in Treg differentiation is accompanied by decreased Hspa13 expression in both Bregs and MZ B cells." (PMID 39737854, 2025). "Hspa13 mRNA was increased in B220+ cells from patients with systemic lupus erythematosus (SLE)." (PMID 32547538, 2020). "Importantly, Hspa13 mRNA was increased in B220+ cells from patients with multiple myeloma (MM) or SLE, whereas Hspa13 cKO led to reduced autoantibodies and proteinuria in both pristane-induced lupus and lupus-prone MRL/lpr mouse models." (PMID 32547538, 2020).
hepatocellular carcinoma (2 papers, 2023). A malignant tumor that arises from hepatocytes. "Studies have shown that HSPA13 is overexpressed in colon and hepatocellular carcinoma tissues." (PMID 37587463, 2023). "HSPA13, an important member of the heat shock protein family, plays an essential role in the oncogenesis of many organs, but the mechanism and function in hepatocellular carcinoma (HCC) is still unclear." (PMID 38062023, 2023).
multiple myeloma (2 papers, 2020 to 2021). "Hspa13 mRNA was increased in B220+ cells from patients with multiple myeloma (MM)." (PMID 32547538, 2020).
acute myeloid leukemia (1 paper, 2020). Acute myeloid leukemia (AML) is a group of neoplasms arising from precursor cells committed to the myeloid cell-line differentiation. "By contrast, there are few reports on ARHGEF3 and HSPA13 in chickens, most of the articles about the ARHGEF3 are related to disease in human, such as acute myeloid leukemias, nasopharyngeal carcinoma cell pathogenesis and platelet function, as for HSPA13, few studies in NCBI database." (PMID 31744899, 2020).
breast carcinoma (1 paper, 2023). "In addition to this, HSPA13 promotes invasion and metastasis of breast cancer cells by regulating angiogenesis and nutrient supply." (PMID 38062023, 2023).
cutaneous melanoma (1 paper, 2023). A primary melanoma arising from atypical melanocytes in the skin. "Moreover, HSPA13 is a risk gene in cutaneous melanoma and is associated with poor patient prognosis." (PMID 38062023, 2023).
latent infection (1 paper, 2023). "On the other hand, the expression of lncRNAs lnc-XPNPEP1-5, lnc-CASKIN2-2, lnc-HSPA13-6, lnc-CLIC5-1, and LINC02502 was significantly reduced in both the latent infection group and the TB patient group compared to the uninfected HC group (all P-values < 0.05)." (PMID 38156018, 2023).
periodontitis (1 paper, 2025). An acute or chronic inflammatory process that affects the tissues that surround and support the teeth. "While studies linking HSPA13 to PD are limited, this study reveals for the first time a significant upregulation of HSPA13 in periodontitis tissues, suggesting its potential involvement in disease pathogenesis." (PMID 41459503, 2025). "We not only identified a novel set of ISR-related biomarkers—BTG2, DERL3, FOS, HSPA13, and YOD1—but also revealed their potential associations with periodontitis-specific pathological features, such as osteoclast differentiation and the RANKL/OPG signaling pathway." (PMID 41459503, 2025). "In this study, BTG2, DERL3, FOS, and HSPA13 were significantly upregulated, and YOD1 was significantly downregulated in the gingival tissues of periodontitis patients, confirming their detectable presence locally." (PMID 41459503, 2025).
prion disease (1 paper, 2023). A transmissible disease that is caused by a protein that is able to induce abnormal folding of normal cellular proteins, leading to characteristic spongiform brain changes, which are associated with neuronal loss without an inflammatory response. "In addition, HSPA13 induces prion diseases, implying that HSPA13 may be associated with abnormal protein folding diseases." (PMID 38062023, 2023).
prostate carcinoma (1 paper, 2025). A carcinoma that arises from epithelial cells of the prostate gland. "HSPBP1 expression was significantly higher in prostate cancer groups than in normal controls, while HSPA13 and HSPB8 showed lower expression levels among prostate cancer tissues." (PMID 41190325, 2025). "First, we employed the downloaded gene matrix to compare the expression of HSPB8, HSPBP1 and HSPA13 levels between normal and prostate cancer samples for validation purposes." (PMID 41190325, 2025). "However, pan-cancer data from GEPIA showed significant differences in terms of HSPB8 expression between normal prostatic tissues and prostate cancer samples while this was not the case for HSPBP1 and HSPA13." (PMID 41190325, 2025).
retinal degeneration (1 paper, 2023). Degeneration of the retina. "Hspa13 is a candidate gene for retinal degeneration, and its expression changes may lead to abnormal development of the retina." (PMID 37239365, 2023).
schwannoma (1 paper, 2013). A benign, usually encapsulated slow growing tumor composed of Schwann cells. "In our series, 5 HSPs were deregulated (HSPA12A: 3.31-fold, p=4.34e-4; HSPA13: 2.54-fold, p=0.0035; HSPA4L: 2.38-fold, p=1.17e-4; HSPB6: −2.19-fold, p=5.76e-4; HSPB8: −3.77-fold, p=0.001), suggesting that the CAV1/HSPs interaction may also play a role in schwannomas." (PMID 23354516, 2013).
cancer (4 papers, 2021 to 2025). A tumor composed of atypical neoplastic, often pleomorphic cells that invade other tissues. "HSPA13 is also involved in apoptosis, immune regulation, and signal transduction, with emerging roles in cancer and neurodegenerative diseases." (PMID 41459503, 2025). "The higher HSPA1A, HSPA1B, and HSPA13 expressions were positively correlated with higher cancer stage and tumor grade." (PMID 34059060, 2021). "Besides, the high HSPA1A, HSPA1B, HSPA4, HSPA5, HSPA8, HSPA13, and HSPA14 expressions were inversely associated with the overall survival rate of patients, tumor grade, and cancer stage." (PMID 34059060, 2021).
tumor (2 papers, 2021 to 2023). "HCC patients with high expression of HSPA13 have shorter overall survival and tumor-free survival rates." (PMID 38062023, 2023). "The results revealed that HSPA13 was predominantly expressed in the cytoplasm and in 80% (52/65) of the patients, HSPA13 expression was higher in HCC tissues than in para-tumor tissues." (PMID 38062023, 2023). "Furthermore, survival analysis demonstrated that high expression of HSPA13 was inversely correlated with overall and tumor-free survival." (PMID 38062023, 2023). "Our study aimed to fill this gap and found that HSPA13 promotes the proliferation, migration, and invasion of HCC cells in vitro, and facilitates tumor growth in vivo." (PMID 38062023, 2023). "Based on these findings, we speculate that HSPA13 may promote tumorigenesis by affecting key molecules of EMT, such as decreasing E-cadherin expression and promoting vimentin expression, which in turn promotes EMT and the metastasis of tumor cells." (PMID 38062023, 2023).
infection (1 paper, 2024). The state of being infected such as from the introduction of a foreign agent such as serum, vaccine, antigenic substance or organism. "This fluctuation contrasts with certain HSP70 isoforms, where several are upregulated (e.g., HSPA1L, HSPA2, HSPA5, HSPA9, HSPA12, and HSPA13), while others from the HSP70 family are downregulated post-peak infection phase (Chand, Iyer & Mitra, 2021)." (PMID 39308823, 2024).
HSPA13 also shares sentences with these, for which no sentence is quoted: Alzheimer disease (2 papers); autism (1); autoimmune disease (1); Bartter syndrome type 1 (1); brain diseases (1); Down syndrome (1); endometrium cancer (1); epilepsy (1); lung carcinoma (1); nasopharyngeal carcinoma (1); neurodegenerative disease (1); Obesity (1); stomach cancer (1); viral infection (1).